IL6 (interleukin 6)
Diseases named in the same sentence as IL6 in open-access papers (continued):
Sharing a sentence is not in itself a finding about the gene and the disease.
viral infection (continued). "Viral infections induce a rapid and potent inflammatory response in different cell types, such as macrophages, fibroblastoid cells, and monocytes that is mediated by an early release of inflammatory cytokines, such as TNF-α, IL-6, and IL-8, and secretion of RANTES." (PMID 32463796, 2020). "In addition, NEMO K326R induced higher expression of IFN‐β and IL‐6 upon viral infection and was not affected by expression of MARCH2." (PMID 32935379, 2020). "Nonetheless, no increased risk for viral infections, i.e., respiratory infections such as influenza has been reported with the inhibition of TNF-α, IL-6, IL-17, or IL-23, which are the most frequent cytokine inhibitors currently used for the treatment of IMIDs13." (PMID 32709909, 2020). "However, in contrast to IFNβ, the production of IL-6 upon viral infection was not significantly different between the control- and MTFMT-silenced cells." (PMID 32636430, 2020). "Both doses of GTD could enhance the secretion of IFN-β and IFN-α, but not TNF-α and IL-6 in macrophages after virus infection." (PMID 33776755, 2020). "While IL-6 secretion did not change significantly following (co-)infection, interleukin 8 secretion increased significantly in influenza A mono-infected cells and, therefore, mirrors viral infection in Detroit cells." (PMID 31827195, 2019). "However, the exact relationship between IL-6 and SOCS3, especially the induction and the functional involvement of SOCS3 in regulating IL-6 production during the viral infection, remains unclear." (PMID 31474976, 2019). "Additionally, IL-6, BAFF, and APRIL are cytokines which play crucial roles in B cell survival and differentiation and are primarily produced by astrocytes within the CNS during viral infection and autoimmunity." (PMID 31428102, 2019). "The first barrier to viral infection is the innate immunity, which is comprised of cellular and soluble components including complement, immunoglobulin, erythrocyte and clotting factor binding (depending on species), and inflammatory cytokines (TNF-α, IL-1β, IL-6)." (PMID 30635014, 2019). "In acutely infected IAV patients, serum/plasma levels of IL-6, IL-8, IL-15, and CXCL10 (IP-10) are elevated, and airway epithelial cells and alveolar macrophages release CXCL10 and IL-15 in the lung upon stimulation with IFN-γ, viral infection, or other pulmonary diseases." (PMID 31156653, 2019). "Moreover, GP73 attenuates IFN-β promoter, IFN-stimulated response element (ISRE) and NF-κB promoter and down-regulates IFN-β, IFN-λ1, interleukin-6 (IL-6) and IFN-stimulated gene 56 (ISG56), leading to the repression of host innate immunity and the facilitation of virus infection." (PMID 28394926, 2017). "Hierarchical clustering identified a distinctive innate immune signature in bite sites that was dominated by neutrophil-attracting chemokines (CXCL1, CXCL2, CXCL3, and CXCL5) and the cytokines IL-1β and IL-6, which were not significantly induced by virus infection alone." (PMID 27332734, 2016). "Moreover, proinflammatory cytokines, such as IL-1, IL-8, CXCL10, IL-6, and TNF-α, are known to be released within hours after inflammation challenge and serve as unspecific alarm signals, as they are released during viral infection, asthma and atopic dermatitis." (PMID 21909400, 2011). "Importantly, multiple labs have found that the lack of either IL-21 alone or IL-6 alone did not substantially impact development of Tfh in vivo in the context of protein immunizations or viral infections." (PMID 21423809, 2011). "Therefore, it is likely the production of IL-6, TNF-α and IFN-β by chorion cells in response to influenza virus infection plays a beneficial role in the innate immune mechanisms against the virus infection through the induction of monocyte differentiation to mature macrophages." (PMID 19936095, 2007).
viral infection (continued). "In AdLacZ infected HUVECs, IL-6 and IL-8 mRNA levels exhibited higher and lower increases, respectively, upon TNF-α stimulation compared to uninfected HUVECs, which may be a result of viral infection per se." (PMID 16803639, 2006). "Firstly, data on virus antibodies and proinflammatory cytokines (e.g., interleukin [IL]-1, IL-6, IL-8 and tumor necrosis factor-α) were not available, which would provide a proper insight into the pathophysiological stage of the myocardial injury from viral infection to the immune reaction." (PMID 33664674, 2021). "Here, we reported that epigenetic remodeler ARID1A, a critical component of the mSWI/SNF complex, could bind IRF3 and then was recruited to the Ifn-I promoter by IRF3, thus selectively promoting IFN-I but not TNF-α, IL-6 production in macrophages upon viral infection." (PMID 34315861, 2021). "However in our study both the TLR agonists induced IL-6 and TNF-α secretion at early and late time points (6 hr and 16 hr) which suggests the possible protective immune response mediated by TLR agonists via secretion of pro-inflammatory cytokines during active viral infection." (PMID 25965265, 2015). "Thus IL-6 secretion might represent a means of defense for human biliary epithelial cells to control and to survive the viral infection, explaining why RRV infection did not result in H69 cell lysis in vitro." (PMID 26247025, 2015). "Interleukin-6, acting via STAT3 and STAT1, plays pivotal roles in governing leukocyte infiltration during acute inflammation that may relate to the involvement of IL-6 in antimicrobial host defense and the inability of Il6−/− mice to effectively clear bacterial or viral infections." (PMID 26501341, 2015). "Thus, pro-inflammatory cytokines, inflammatory mediators and substances in the airway mucosa and submucosa, including IL-6, IL-11, ICAM-1, ECP, LTC4, LTD4, and histamine, may induce airway inflammation and smooth muscle contraction in asthma patients with viral infections." (PMID 22966430, 2012). "However due to lack of reagents available to selectively manipulate IL-6 trans-signaling over the course of the 8–10 week viral infection, it is difficult to gauge whether a dual-mode of IL-6 signaling influences the outcome of the anti-influenza response." (PMID 18389078, 2008). "In the absence of viral infection, a temperature switch from 18°C to 28°C for CIK cells, or grass carp in the fish tank, significantly induced the expression of IL6, IL1β, and TNF-α." (PMID 37099596, 2023). "To date, there is no report of the interplay between temperature, IL6/STAT3 signaling, and aquatic virus infection." (PMID 37099596, 2023). "Therefore, high expression of non-ISGs such as IL-6 and ACE2 could be biomarkers for the exacerbation of inflammation underlying some viral infections, especially those such as SARS-CoV-2, which dysregulates the physiological function of ACE2 in the RAAS-centric body systems." (PMID 33503821, 2021). "Virus infection resulted in induced gene expression of IFN-β, IL-1β, IL-6, and IL-8, but surprisingly not IFN-α." (PMID 32265870, 2020). "This is in accord with IL-6-mediated phosphorylation of STAT1 and inhibition of viral infection in LNCaP-JAK1, but not LNCaP, cells." (PMID 29441069, 2018). "It was quite unexpected that many proinflammatory cytokines/chemokines, such as TNF-α and IL-6, were not significantly higher during acute ZIKV infection in an endemic area, in contrast with other viral infections, such as dengue." (PMID 29774022, 2018). "We found that patients with viral infections showed higher levels of TNF-α, IL-6, and MCP-1 than those without." (PMID 28352642, 2017). "Compared with WT macrophages, more cell death occurred in IL-6−/− macrophages in the absence of IAV infection, which were further increased after viral infection." (PMID 28262742, 2017).
viral infection (continued). "This series of experiments indicated that the induction of IL-6 and CCL5 by NH1125B is virus specific, requires viral infection and was not due to some other factor (e.g. virus) in the viral stock preparation." (PMID 28877226, 2017). "In summary, these data indicate a highly specific response of macrophages through a coordinated negative regulation of multiple sterol pathway members upon viral infection or treatment with IFNγ or β but not IL1β, TNF, or IL6." (PMID 21408089, 2011). "As a consequence, levels of pro-inflammatory cytokines and chemokines, such as IL-1β, Il-6, IL-12, CCL2 and CCL3 increased within 24 hours of CL, but not PBS treatment, prior to virus infection." (PMID 19851468, 2009). "By incubating Calu-1 cells with IMD-0354 (without subsequent viral infection), we also observed increased expression of IFN-β, CXCL10, and IL-6 with 15, 9, and 36-folds, respectively; and the activation of these genes was counteracted by BX795, a TBK1/IKKε inhibitor that blocks IFN-β production." (PMID 36093376, 2022). "An increase in IL6 and IL8 production was previously observed upon the interaction of human cervical epithelial cells with T. vaginalis-derived exosomes, however, the status of T. vaginalis viral infection in these experiments was not clarified." (PMID 35602021, 2022). "As shown in our previous studies, together with IL-6, IL-10, and IFN-γ, the cytokine patterns are helpful in discriminating bacterial and virus infection, Gram-positive and negative bacterial infection, and invasive pulmonary aspergillosis and pneumocystis pneumonia." (PMID 35391735, 2022). "Therefore, a strategy that reduces IL-1β, IL-6, and TNF-α levels can control allergic asthma with or without viral infections." (PMID 36501052, 2022). "Numerous studies have already shown increased levels of IL6 and CXCL8 due to diesel exhaust or particulate matter exposure in primary respiratory cells, but not in the context of viral infections as reported in our study." (PMID 34542243, 2021). "B cells are increasingly recognized as being an important source of a number of cytokines in viral infections and other settings, among which both TNF-α and IL-6 could have potent noncytolytic antiviral activity against HBV." (PMID 30091725, 2018). "The cytokines IL-6, IL-10, IL-12, IL-17, TNF-α and IFN-γ were evaluated in the Cerebrospinal fluid (CSF) of patients with meningoencephalitis with and without viral infections as well as in control CSF samples using the cytometric bead array (CBA – BD biosciences)." (PMID 26286516, 2015). "Similarly, protein expression of IL6 and IL8 was significantly induced upon viral infection, but no significant differential expression was observed between asthma and non-asthma groups." (PMID 25706956, 2015). "Further analysis also showed that while the production of IL-6 and IL-10 are dependent on viral replication, production of TNF-α also occurs after exposure to UV-inactivated TCRV particles and is thus independent of productive virus infection." (PMID 21572983, 2011). "In time-series experiments profiling genome-wide lipid-associated gene expression of macrophages, we show a selective and coordinated negative regulation of the complete sterol pathway upon viral infection or cytokine treatment with IFNγ or β but not TNF, IL1β, or IL6." (PMID 21408089, 2011). "However, after viral infection, CINNA could reduce IL-1β levels but not significantly counteract the IL-6 one." (PMID 37986089, 2023). "Therefore, it is suggested that NP may be increased independent of IL-6 and CRP elevation in cases of viral infection." (PMID 35529699, 2022). "Here we show that absence of IL-6 reduces EV-A71 lethality, the damage in the CNS, and tissue viral loads with increased levels of CD4 T cells in the spleen and virus-specific neutralizing antibody in the serum in a manner rarely reported in other virus infections." (PMID 29233145, 2017).
periodontitis (988 papers, 2007 to 2026). An acute or chronic inflammatory process that affects the tissues that surround and support the teeth. "In particular, IL6 is a proinflammatory cytokine frequently implicated in tumour progression, metastasis and periodontitis." (PMID 41055332, 2026). "These cytokines (such as TNF‐α, IL‐6, IL‐1β, and IL‐17) play a role in the bone destruction pathway of periodontitis and can cause bone resorption by regulating osteoclast formation." (PMID 40761494, 2025). "In response to elevated PGE, TNF-α, IL-1 and IL-6, periodontitis causes the liver to produce more CRP, especially in early pregnancy." (PMID 41394354, 2025). "Elevated IL-6 levels have been associated not only with periodontitis but also with systemic inflammatory conditions such as obesity, diabetes, and cardiovascular disease." (PMID 41007333, 2025). "Periodontitis, the leading cause of adult tooth loss, triggers chronic low-grade inflammation, marked by elevated levels of interleukin-6 (IL-6) and C-reactive protein (CRP), two biomarkers consistently linked to frailty, sarcopenia, and functional impairment." (PMID 41398005, 2025). "This study aimed to compare salivary levels of cortisol, interleukin-1β, and interleukin-6 in patients with varying periodontitis severity and examine their associations with clinical periodontal parameters." (PMID 40843742, 2025). "As an important inflammatory cytokine, interleukin-6 (IL-6) can mediate the entire pathological process of periodontitis and is closely associated with the degree of inflammation." (PMID 40242657, 2025). "Similar to periodontitis, inflammation in periimplantitis is associated with elevated levels of pro-inflammatory cytokines such as interleukin-1β (IL-1β), interleukin-6 (IL-6), and tumor necrosis factor-alpha (TNF-α)." (PMID 40217900, 2025). "This study presents novel insights into the diagnostic and pathophysiological relevance of salivary IL-6 and irisin levels in Stage 3 Grade C periodontitis." (PMID 41007333, 2025). "Genetic polymorphisms mostly associated with periodontitis are those of genes coding for IL-1, IL-6, and TNF-α but, as already mentioned, the existing studies often gloss over inconsistent replication across ethnicities." (PMID 41300760, 2025). "Biologic agents that neutralize specific cytokines like TNF-α or IL-6 have demonstrated efficacy in preclinical periodontitis models but carry the risk and cost associated with systemic immunosuppressive therapies." (PMID 41333482, 2025). "In our experiments, we observed elevated levels of serum pro-inflammatory cytokines (IL-17A, IL-1β, IL-6, IL-8) associated with periodontitis." (PMID 40732209, 2025). "This inflammatory state is exacerbated by elevated levels of pro-inflammatory markers, such as C-reactive protein (CRP), tumor necrosis factor-alpha (TNF-α), and interleukin-6 (IL-6), commonly associated with both periodontitis and cardiovascular diseases." (PMID 40066344, 2025). "Currently, SNP analysis and GWAS have detected genes polymorphisms associated with periodontitis in genes coding for pro-inflammatory cytokines, including IL-1, IL-6, TNF-α, and others involved in immune modulation and bone metabolism." (PMID 41300760, 2025). "Consistent with these interventional findings, periodontitis is also associated with endothelial dysfunction and vascular inflammation, accompanied by elevated neutrophil counts and circulating IL-6 and C-reactive protein (CRP)." (PMID 41515997, 2025). "In the control group, a significant correlation was observed between BMI and IL-6 (r = 0.429, p = 0.013), whereas in the periodontitis group, IL-6 levels were significantly associated with PI values (r = 0.403, p = 0.020)." (PMID 41007333, 2025). "Accordingly, IL-6 promotes osteoclast bone resorption and plays a crucial role in the etiology of bone loss in acute and chronic inflammation, periodontitis, osteoporosis, and rheumatoid arthritis." (PMID 40724937, 2025).
periodontitis (continued). "IL-6 is associated with chronic inflammation, contributing to periodontal damage, periodontitis, Sjögren's syndrome, and oral squamous cell carcinoma (OSCC)." (PMID 40771401, 2025). "Dysregulated IL-6 signaling therefore represents a central mechanism linking the molecular inflammatory response to the clinical hallmarks of periodontitis, including pocket formation, attachment loss, and progressive tissue destruction." (PMID 41007333, 2025). "IL-6 plays a central role in orchestrating the host immune response and is closely associated with tissue destruction in periodontitis." (PMID 40725050, 2025). "In periodontitis, the inhibition of IL-6 has been shown to reduce inflammatory bone loss in experimental models." (PMID 40647649, 2025). "For instance, IL-6 and IL-23 secreted by M1 macrophages can promote the expansion of pathogenic Th17 cells, exacerbating periodontitis." (PMID 40370404, 2025). "Ligature‐induced periodontitis and diabetic models: liraglutide decreases bone loss, improves microarchitecture, and lowers IL‐6, TNF‐α, and IL‐1β." (PMID 41328144, 2025). "Despite accounting for confounding factors such as smoking, studies consistently show significant associations between serum levels of CRP and IL-6 and periodontitis." (PMID 40136726, 2025). "Elevated levels of IL-6 in periodontal tissues are strongly associated with the progression of periodontitis and the destruction of the periodontal attachment." (PMID 40085302, 2025). "Shared molecular pathways can lead to LGSI, where the overproduction of ROS and pro-inflammatory mediators such as TNF-α and IL-6 negatively impact periodontal tissues, increasing susceptibility to the onset and progression of periodontitis." (PMID 41284085, 2025). "Its role in periodontitis is complex, as elevated IL-6 levels have been associated with disease severity and systemic inflammation, yet IL-6 also participates in the initial protective immune responses to bacterial invasion." (PMID 41155385, 2025). "In the past, IL-6 has been linked to the acute and initial phases of periodontitis with significant overexpression." (PMID 38541692, 2024). "In the present study, increased levels of IL-6 in both periodontitis groups suggested that these markers are directly associated with periodontal inflammation and tissue destruction; however, this significance was not maintained among periodontitis stages." (PMID 39215253, 2024). "Among the leakage of microbial products, the spread of inflammatory cytokines such Il-6 occurs; this is a cytokine that is connected to bone loss in periodontitis and which has also been linked to joint erosion in RA patients and other inflammatory diseases." (PMID 39336457, 2024). "Ovariectomized rats exhibit greater osteoclast activity and bone loss following ligature-induced periodontitis, and similar effects are seen in sheep, with increased alveolar bone loss and higher IL-6 levels in diseased sites one year post-ovariectomy." (PMID 39917660, 2024). "This narrative review explores the significant role of IL-6 in patients with periodontitis and its association with other widespread inflammatory pathologies." (PMID 38396821, 2024). "Inflammatory markers such as cytokines for example, IL‐1β, IL‐6, which are elevated in saliva and gingival crevicular fluid, have been implicated in both periodontitis and OSA." (PMID 38433299, 2024). "Among extensively studied salivary biomarkers, the combination of MMP-8 and IL-6 has shown the highest diagnostic accuracy for periodontitis." (PMID 39554809, 2024). "TCZ in rats with lab-induced periodontitis clearly depicted reduced the bone loss levels and inflammatory signs due to the reduction in IL-6 levels." (PMID 38396821, 2024). "Taken together, these results suggested that in the saliva of our participants, the two determinant factors (ACE2 and IL-6) associated with periodontitis in vaccinated individuals were relatively dependent." (PMID 39917640, 2024).